PTH (parathyroid hormone)
Diseases named in the same sentence as PTH in open-access papers (continued):
Sharing a sentence is not in itself a finding about the gene and the disease.
hypoparathyroidism (continued). "Peripheral resistance to PTH action resulting in functional hypoparathyroidism is known as pseudohypoparathyroidism." (PMID 29694629, 2018). "From a functional point of view, hypoparathyroidism arises from an inability of the parathyroid glands in secreting PTH and/or impaired PTH action, directly impacting the homeostasis of calcium and phosphorus." (PMID 29694629, 2018). "Hypoparathyroidism resulting from peripheral resistance to PTH action is known as pseudohypoparathyroidism." (PMID 29694629, 2018). "All these patients who had either an inappropriately low or normal serum PTH were considered to have hypoparathyroidism." (PMID 29726397, 2018). "Administration of PTH-secreting tonsil-derived stem cells with plasma gel is highly feasible treatment modality for treating hypoparathyroidism patient." (PMID 30093637, 2018). "Median plasma FGF-23 level in patients with hypoparathyroidism was significantly lower than that of normoparathyroid patients (34.8 vs 43.1 pg/mL, p=0.048) although serum P levels and serum PTH levels were comparable." (PMID 29726397, 2018). "Hypoparathyroidism (HPT) is the partial or complete reduction of parathyroid hormone (PTH) secretion from the parathyroid glands." (PMID 28993435, 2017). "Serum PTH level of hypoparathyroidism varied from 1 to 59.18 pg/mL (12.28 ± 17.59 pg/mL); the level of pseudohypoparathyroidism varied from 99.39 to 868.00 pg/mL (436.10 ± 262.56 pg/mL)." (PMID 27957632, 2017). "From a nephrologist perspective, it is also worth noting that hypomagnesemia (e.g. during chronic cyclosporine or diuretic treatment) inhibits parathyroid hormone secretion and can mimic hypoparathyroidism." (PMID 27384692, 2017). "In hypoparathyroidism, inappropriately low levels of parathyroid hormone lead to unbalanced mineral homeostasis." (PMID 27734257, 2017). "Depending on the definition based on calcium alone or on calcium in combination with PTH, there have been variations in reporting temporary and permanent hypoparathyroidism in various studies, thus making it difficult to compare the complication rates." (PMID 27393573, 2016). "PTH replacement therapy has been demonstrated to ameliorate the blood, renal, skeletal and neuropsychological features of hypoparathyroidism to a greater extent than conventional treatment." (PMID 27857062, 2016). "A standardized protocol was applied in the current study to diagnose and define temporary and permanent postoperative hypoparathyroidism based on PTH levels after TT." (PMID 27393573, 2016). "As for the level of postoperative parathyroid hormone, temporary hypoparathyroidism was found in 28 (14.7%) patients." (PMID 28074094, 2016). "It has been shown that administration of PTH by pump delivery can increase bone mass in children suffering from severe hypoparathyroidism, but many studies show that continuous administration of PTH can lead to bone loss, e.g., Ref." (PMID 27379013, 2016). "Because PTH plays a role in bone resorption, hypoparathyroidism patients exhibit higher bone volume than individuals with a normal PTH level." (PMID 27695051, 2016). "This surgical technique successfully produced a hypoparathyroidism animal model that was documented by post-operative PTH decreasing rapidly to an undetectable level." (PMID 27695051, 2016). "Hypoparathyroidism is mainly an acquired disease, characterized by low or inappropriately normal levels of PTH, resulting from damage or surgical excision of the parathyroid glands or autoimmune mechanisms." (PMID 27415614, 2016). "Although ADH is associated with increased circulating phosphate concentrations and inappropriately low or normal PTH concentrations, this is considered to represent a distinct disease entity from hypoparathyroidism." (PMID 27647839, 2016).
hypoparathyroidism (continued). "With the increasing preference for shorter hospital stays, measurement of intact PTH alone or in combination with other biochemical parameters after total thyroidectomy has been used recently as a predictor of postoperative hypoparathyroidism." (PMID 25691901, 2015). "The study encourages further investigation to determine the role of PTH as hormone replacement therapy in postsurgical hypoparathyroidism." (PMID 23286605, 2013). "Paraclinical tests demonstrated that the patients had low calcium, high phosphate, and low PTH levels; a diagnosis of hypoparathyroidism was, therefore, established for the patient." (PMID 24174700, 2013). "In contrast, 6 of 14 patients with PTH-SC ≤1 pmol/L required both oral calcium and calcitriol and 2 eventually developed permanent hypoparathyroidism." (PMID 22399155, 2012). "Hypoparathyroidism improved with oral calcium supplementation with subsequent normal serum intact parathyroid hormone levels." (PMID 23148801, 2012). "Treatment of hypoparathyroid patients with synthetic PTH is controversial and its effectiveness in our patient is questionable as well." (PMID 22251708, 2012). "Pseudohypoparathyroidism (PHP) is a rare hereditary disorder resembling hypoparathyroidism, although plasma PTH levels are elevated." (PMID 22937298, 2012). "Of these six patients, two suffered permanent hypoparathyroidism and their PTH-SC values were 0.6 and 0.7 pmol/L, respectively." (PMID 22399155, 2012). "In latent hypoparathyroidism PTH is secreted in sufficient quantities in basal states and serum calcium (Ca) and phosphorus (P) levels are normal." (PMID 21274400, 2009). "Hypoparathyroidism is a clinically heterogeneous condition, where biochemical markers like PTH and calcium are essential for diagnosis, but symptom severity varies widely and may not align with laboratory values." (PMID 41229353, 2025). "In fact, hypoparathyroidism has been associated with reduced bone turnover and mineralization due to the absence of the effect of PTH on osteoblasts." (PMID 39851484, 2025). "Additionally, 9 thyroidectomy patients (2.6%) had PTH levels less than the institution’s reference range by the last follow-up, indicating a low rate of hypoparathyroidism." (PMID 40668552, 2025). "This problem could likely be resolved with a greater focus on postsurgical hypoparathyroidism among oncologists, or with routine postoperative PTH measurements before hospital discharge to ensure an early diagnosis of hypoparathyroidism." (PMID 40587027, 2025). "Hypoparathyroidism is a metabolic disorder caused by lack of parathyroid hormone,which leads to hypocalcaemia and hyperphosphataemia." (PMID 40838538, 2025). "Epfn may therefore be a drug target factor potentially capable of inhibiting PTH transcription even in hypocalcemic conditions, such as in patients with secondary hypoparathyroidism." (PMID 40164571, 2025). "The ICG group had a lower rate of inadvertent parathyroidectomy (9% vs. 17.9% in the standard group, chi-square test, p = 0.015), a lower rate of postoperative hypoparathyroidism (18.6% vs. 35.3%, chi-square test, p = 0.001), and higher postoperative PTH levels (t-test, p = 0.0001)." (PMID 40426871, 2025). "The normal parathyroid hormone levels in this patient could reflect either incomplete penetrance of the hypoparathyroidism phenotype or secondary regulatory effects from CKD." (PMID 41019281, 2025). "The difference in the incidence rates can be explained on the basis of the difference in the number of patients in their study compared to our study and the lower cut-off value of serum PTH level <10 pg/mL to label hypoparathyroidism (<15 pg/mL in the present study)." (PMID 39996189, 2025). "However, in children, low or inappropriately normal PTH levels suggest hypoparathyroidism as an important differential diagnosis." (PMID 41322012, 2025).
hypoparathyroidism (continued). "Statement 21: Serum PTH level (when possible) should be obtained within 24 h after total or completion thyroidectomy as an obligatory surrogate biochemical marker of postoperative hypoparathyroidism." (PMID 41229353, 2025). "Using a cutoff value of 10 pg/mL for PTH, hypoparathyroidism was diagnosed in 47 patients (31.8%)." (PMID 40091995, 2025). "While the majority of cases are transient and resolve within weeks, a substantial proportion (up to 25%) progress to persistent hypoparathyroidism, defined by sustained reductions in parathyroid hormone (PTH) and serum calcium levels beyond 6–12 months after surgery." (PMID 41229353, 2025). "Statement 21A: Patients with normal PTH serum levels on POD1 have a very low risk of permanent hypoparathyroidism and are expected to need minimal monitoring and no calcium supplementation at discharge." (PMID 41229353, 2025). "The study suggests that early PTH measurement may serve as a useful predictor for permanent hypoparathyroidism, though further research is needed to confirm its reliability and refine treatment protocols." (PMID 41229353, 2025). "Therefore, our prediction is consistent with previously suggested therapeutic approaches based on the use of long-acting PTH derivatives to treat hypoparathyroidism patients." (PMID 40392940, 2025). "Parathyroid hormone levels < 11 pg/mL were considered to indicate transient hypoparathyroidism." (PMID 41199844, 2025). "In mitochondrial diseases, including KSS, hypoparathyroidism is thought to result from a combination of renal tubular electrolyte losses and direct mitochondrial dysfunction in parathyroid cells, leading to impaired energy-dependent PTH secretion." (PMID 41480351, 2025). "Therefore, low or insufficient secretion or action of PTH leads to hypoparathyroidism; biochemically, this will show as low PTH, low calcium, and high phosphate." (PMID 41295288, 2025). "Statement 6: Temporary postoperative hypoparathyroidism is a condition that usually resolves within the first 6 months after surgery (but sometimes can last up to 12 months) with PTH and serum calcium levels within the reference range, without calcium and/or active vitamin D analogue supplements." (PMID 41229353, 2025). "Hypoparathyroidism is a metabolic condition resulting from a deficiency or absence of parathyroid hormone secretion, characterized by low serum calcium and elevated serum phosphorus levels." (PMID 39981459, 2025). "In addition, the incidence of inadvertent parathyroidectomy as well as transient postoperative hypoparathyroidism (defined as PTH < 1.5 pmol/L) was reduced in the ICG group compared to the conventional group." (PMID 40426871, 2025). "Following kidney transplantation, renewed attention to calcium, phosphate, and PTH is required because hypoparathyroidism may re-emerge or become unmasked as renal function improves." (PMID 41531582, 2025). "Monitoring PTH levels can also provide valuable insights; a low PTH level alongside low calcium indicates hypoparathyroidism, while normal PTH levels with low calcium may suggest other underlying issues." (PMID 39258042, 2024). "With these premises, reproducible animal models of hypoparathyroidism are necessary to dissect the specific effects of PTH deprivation, particularly in the view of treatments such as human recombinant PTH (rhPTH) administration, which has become available but still used only with few indications." (PMID 38392648, 2024). "Hypoparathyroidism is a rare endocrine disorder caused by the reduced or absent production of parathyroid hormone (PTH) by the parathyroid glands, which leads to low calcium and high phosphate serum concentrations." (PMID 37819413, 2024). "The findings represent a significant advancement in parathyroid organoid culture and may offer a cellular therapy for treating PTH‐related diseases, including hypoparathyroidism." (PMID 39331961, 2024).
hypoparathyroidism (continued). "Conversely, hypoparathyroidism features low calcium, high serum phosphate, and low PTH levels." (PMID 39328612, 2024). "Notably, our findings underscored a substantial correlation between total thyroidectomy (OR = 21.5, P < 0.001), diminished PTH levels (P < 0.001), and the occurrence of postoperative hypoparathyroidism." (PMID 40071247, 2024). "Functional hypoparathyroidism and PTH resistance, which have been reported in critically ill patients, may also be relevant in COVID-19 cases." (PMID 39262524, 2024). "The authors speculated that PTH could be a new therapeutic strategy for the regulation of different skeletal muscle processes in patients affected by hypoparathyroidism and showing muscle dysfunction." (PMID 37819413, 2024). "Moreover, 26.9 (19.9 to 34.9) per cent of all patients with an immediate low PTH level developed definitive permanent hypoparathyroidism." (PMID 37995259, 2024). "In this study, it was proposed that the rate of patients with a low postoperative PTH level within 1–24 h after surgery may correspond to the rate of permanent hypoparathyroidism in a cohort." (PMID 37995259, 2024). "The secondary aims were to assess the relationship between an immediate postoperative surrogate marker, serum parathyroid hormone (PTH), and the risk of permanent hypoparathyroidism in the total cohort and to validate the reported data on complications in the SQRTPA." (PMID 37995259, 2024). "The rate of low PTH level in the first 24 h after surgery might be a promising surrogate for the rate of permanent hypoparathyroidism in a cohort." (PMID 37995259, 2024). "Hypoparathyroidism was defined as PTH < 12 pg/dL in their study." (PMID 38472977, 2024). "Additionally, our report represents real-world experiences and outcomes in managing patients with hypoparathyroidism by transitioning from conventional therapy to single/multiple daily PTH injections and subsequent PTH pump treatment." (PMID 38562130, 2024). "Furthermore, a randomized controlled trial in patients with hypoparathyroidism treated with recombinant PTH versus placebo showed that the PTH-treated group had a significant increase in (decarboxylated) osteocalcin." (PMID 37819413, 2024). "Furthermore, 10 per cent with a low PTH value would correspond to a 2.9 (1.9 to 3.5) per cent rate, and 5 per cent to a 1.4 (1.0 to 1.7) per cent rate, of permanent hypoparathyroidism." (PMID 37995259, 2024). "The chronicity of his disease is not typical of alcohol-induced hypoparathyroidism, which tends to be transient, occurring due to alcohol-driven magnesium deficiency, which subsequently causes a reduction in PTH excretion." (PMID 39742164, 2024). "Hypoparathyroidism is an endocrine disease caused by insufficient or absent production of parathyroid hormone (PTH) with multiorgan involvement." (PMID 36271471, 2023). "Normal parathyroid hormone and calcium levels in the patient's serum ruled out hypoparathyroidism or pseudohypoparathyroidism as causes for the intracranial calcifications." (PMID 37780723, 2023). "Ca2+, PTH levels and risks of hypoparathyroidism in PUS Group and Control Group." (PMID 36923217, 2023). "An evaluation of the PTH levels would maybe have provided a better estimate of the true rate of permanent clinical hypoparathyroidism." (PMID 38201609, 2023). "Case reports describing calciphylaxis with hypoparathyroidism attribute the aetiology to complications of calcium management, with calciphylaxis commonly being triggered by treatment with vitamin D analogues or recombinant PTH." (PMID 38064896, 2023). "Finally, it has been reported that PTH, when used to treat adult patients with hypoparathyroidism, induces an improvement in mental and physical performance." (PMID 37189637, 2023). "PTH replacement therapy is the ideal physiologic treatment for hypoparathyroidism." (PMID 36271471, 2023).
hypoparathyroidism (continued). "These methods include the detection of serum ions or PTH levels in serum before, during, and after surgery, which can predict whether permanent or transient hypoparathyroidism will occur in postoperation." (PMID 37091845, 2023). "The number of patients with PTH less than the minimum detection range (1.2 pg/ml) within three days after surgery was 60 (20.8%), 13 (21.7%) of whom developed permanent hypoparathyroidism; only 8 (7.3%) of the remaining 110 patients with hypoparathyroidism developed permanent hypoparathyroidism." (PMID 37545843, 2023). "Early after PT surgery, normal or high (but lower than pre-operatory level) parathyroid hormone (PTH) is essential for establishing HBS diagnostic since non-low PTH is the clue to differentiate the condition from post-surgery hypoparathyroidism (low PTH)." (PMID 37296804, 2023). "Hypoparathyroidism is a relatively rare human and veterinary disease characterized by deficient or absent production of parathyroid hormone (PTH)." (PMID 37180074, 2023). "Staining with NC or ICG angiography could reduce the possibility of accidental parathyroid excision, thereby decreasing the occurrence of hypoparathyroidism, while facilitating the rapid restoration of PTH and calcium levels." (PMID 36439530, 2022). "Chronic postsurgical hypoparathyroidism may be predicted by serum PTH <10 pg/mL in the first 12-24 hours after surgery." (PMID 36382749, 2022). "Hypoparathyroidism was considered permanent if the plasma parathyroid hormone (PTH) levels at 6 months were less than 15 pg/mL and the patient still required oral calcium (calcium carbonate) and vitamin D supplementation, in addition to the supplements that were taken routinely before thyroidectomy." (PMID 35565776, 2022). "Two recombinant PTH structures have to be combined and can be utilized to treat hypoparathyroidism." (PMID 36381723, 2022). "TransCon technology has also been applied to create sustained release prodrugs of human parathyroid hormone (TransCon PTH) for hypoparathyroidism and of C-type natriuretic peptide (TransCon CNP) for achondroplasia, both of which are currently in late-stage clinical development." (PMID 36123697, 2022). "The ideal PTH replacement therapy for hypoparathyroidism is an autograft of parathyroid glands." (PMID 35203648, 2022). "Thus, we further stratified patients in the individual groups into two separate subgroups based on the patients’ postoperative PTH levels, either the normal parathyroid function (PTH, ≥1.3 pmol/L) or the hypoparathyroidism group (PTH, <1.3 pmol/L)." (PMID 36091150, 2022). "These rates may have been lower in previous studies due to differences in the definition of hypoparathyroidism, postoperative time points at which PTH was measured, and the proportion of pathological malignancy." (PMID 35311081, 2022). "Hypoparathyroidism (HypoPT) is a rare endocrinological disease characterized by serum calcium or ionized calcium concentration below the normal range, accompanied by undetectable or inappropriately low levels of parathyroid hormone (PTH)." (PMID 35460461, 2022). "We conducted a literature search using the PubMed database and textbooks to identify articles, guidelines, and consensuses using the keywords “hypoparathyroidism”, “treatment”, and “management” as well as specific terms, such as “PTH analogs” and “calcilytics”." (PMID 36382754, 2022). "Additional research is needed to explore clinical application of this parathyroid culture methodology because one day these PTOs may serve as a stem cell transplantation method for patients with abnormally low levels of PTH (hypoparathyroidism)." (PMID 36306782, 2022). "Most (24/30) patients with permanent hypoparathyroidism had POD1 PTH levels < 10 pg/ml." (PMID 35247092, 2022). "However, in their study, hypoparathyroidism was defined as PTH <10 pg/ml, and PTH levels were measured in the immediate postoperative period (<2 weeks)." (PMID 35311081, 2022).